EGFR (epidermal growth factor receptor)
Diseases named in the same sentence as EGFR in open-access papers (continued):
Sharing a sentence is not in itself a finding about the gene and the disease.
tumor (continued). "There is a class of anticancer drugs called EGFR inhibitors, which can specifically inhibit the activity of EGFR or prevent the binding of EGFR to its ligands, thus inhibiting the activation of its downstream signaling pathway and achieving the goal of inhibiting tumor growth." (PMID 38562672, 2024). "Furthermore, we observed an upregulation of FAK in specific tumor types with gene mutations or aberrant protein expression, such as BRAF/KRAS mutations, CDH1 deletions, EGFR or HER2 overexpression, and mediated drug resistance processes." (PMID 38410129, 2024). "Also, EGFR signaling pathway can be a mediator of immune escape and promote the progression of neoplasms, also an influencing factor regarding the prognosis of immunotherapy." (PMID 38972967, 2024). "It was indicated that EGFR-TKIs impact the tumor immune microenvironment." (PMID 38674427, 2024). "Besides its role in tumorigenesis, the Hippo pathway plays a pivotal role in drug resistance of NSCLC via crosstalk with other well-known tumor-promoting factors such as EGFR, ALK, BRAF, KRAS, and ROS1." (PMID 38499647, 2024). "We speculated that the tissue microstructure complexity (such as tumor cell density, tumor interstitial volume, and membrane structure complexity) of EGFR wild type may be significantly different from mutant type." (PMID 38396128, 2024). "Nevertheless, our study highlights the effectiveness of simultaneous genomic and transcriptomic profiles of HR+/HER2-BC at the single-cell level, with particular focus on the migratory SC-f tumor subtype in relation to EGFR genomic aberration and the interplay between CAFs." (PMID 38892065, 2024). "This was followed by the discovery of cellular counterparts of further viral oncogenes, tumor drivers initially identified in retroviruses, including MYC, RAF, ERBB1 (encoding Epidermal growth factor receptor [EGFR]), AKT, and SIS (encoding subunit B of the platelet-derived growth factor [PDGF])." (PMID 38920700, 2024). "NRP1 can drive tumor progression by activating the RAS-MAPK pathway via EGFR and PDGFR." (PMID 38728245, 2024). "Similarly, epidermal growth factor receptor (EGFR), another crucial actor of tumor cell growth and survival, was targeted by such an approach." (PMID 39598465, 2024). "Finally, the network pharmacological analysis of the processing biomarkers predicted that the key anti-tumor pathway of black ginseng was EGFR/PI3K/Akt/mTOR." (PMID 39200424, 2024). "The landscape of metastatic colorectal carcinoma (mCRC) witnessed a significant development in 2006 with the approval of panitumumab, a fully human IgG2 monoclonal antibody, for third-line treatment in cases where the tumor expresses epidermal growth factor receptor (EGFR)." (PMID 38844562, 2024). "In addition, simultaneous targeting of EGFR and integrin αvβ3 receptors can effectively regulate tumor cells and the tumor ECM." (PMID 38690275, 2024). "The enhancement of HER2/HER2 homodimers and HER2/EGFR heterodimers internalization may lead to reduction in signal transductions and gene expressions that favor tumor development, proliferation, progression, migration and survival." (PMID 38982548, 2024). "CD109 may amplify this process, as it interacts with EGFR to activate the Akt/mTOR pathway, driving tumor growth." (PMID 39990858, 2024). "No oncogenic drivers were identified (analysis performed on tumor tissue sample through polymerase chain reaction testing EGFR and KRAS mutations)." (PMID 38392077, 2024). "In our clinical pipeline, a molecularly engineered recombinant anti-CD3 x anti-EGFR BiAb (rEGFRBi) with deletion of the sequence responsible for allergic reactions, has markedly enhanced cytotoxicity, and induced Th1 cytokine secretion when engaging multiple EGFR + tumor cell lines including GBM." (PMID 38263486, 2024).
tumor (continued). "Our data collectively suggested that EREG plays an important role in the cancer microenvironment under the influence of LPS to increase not only the tumor cell growth and migration/invasion of EGFR-positive HCC cells but also tumor neovascularization via IL-8 signaling." (PMID 38673992, 2024). "In addition to the clearance of EGFR from the tumor cell surface, this antibody can indirectly impair tumor growth, inhibiting further angiogenesis, invasion, and metastasis by targeting the tumor stroma." (PMID 39000238, 2024). "Upregulation of PD-L1 in tumor cells and in the tumor microenvironment by radiotherapy is a complex mechanism and thought to be through four pathways: Interferon γ signaling, epidermal growth factor receptor pathway, DNA damage signaling pathway, and cGAS-STING pathway." (PMID 39026981, 2024). "Similarly, in case NCCLu-045, the patient’s tumor successfully responded to re-treatment with an EGFR-TKI." (PMID 38398169, 2024). "The genetic profile of EGFR may predict tumour response to radiotherapy and this information can be used to optimize radiotherapy schedules by reducing the total dose, which can also lower the risk of potential toxicity." (PMID 39132508, 2024). "Tumor growth was inhibited after treatment with EGFR siRNA LPX + UTMC." (PMID 38577322, 2024). "In addition, EGFR expression is significantly elevated and dysregulated in a variety of neoplastic diseases." (PMID 38434350, 2024). "Overall, these results suggest that Z239-1907 dual-target affibody may be promising for Axl-EGFR targeted therapy and molecular probe for tumor imaging in NPC." (PMID 39594573, 2024). "The epidermal growth factor receptor (EGFR) signaling pathway is considered to play a pivotal role in cell proliferation, survival, and apoptosis, being involved in many types of neoplasms and even being associated with sensitivity to chemotherapeutic evaluation." (PMID 38672615, 2024). "However, mutations in both EGFR and KRAS showed unique allelic differences determined by smoking status that are known to alter tumor response to targeted therapy." (PMID 39052387, 2024). "We observed that EGFR expression was restricted to the fetal tumor regions." (PMID 39567475, 2024). "Consequently, the synergistic combination of KRAS G12C inhibitors and anti-EGFR therapies was investigated both in vitro and in colorectal patient-derived models, yielding significant tumor regression or even complete remission." (PMID 38542278, 2024). "Moreover, FAP and EGFR have been shown to enhance T cell activation and accumulation at the tumor site, thereby increasing anti-tumor efficacy." (PMID 39055561, 2024). "Further studies evaluating the tumor microenvironment differences in patients receiving 3rd generation EGFR TKIs versus 1st /2nd generation EGFR TKIs are warranted to help illustrate how 3rd gen TKIs may be more efficacious." (PMID 39483887, 2024). "HSP90 also stabilizes the epidermal growth factor receptor (EGFR) in tumor cells." (PMID 39148727, 2024). "Also in the context of cancer, exosomal miR-148a-3p was shown to promote tumor angiogenesis through activation of the EGFR/MAPK signaling pathway by ERRFI1 inhibition." (PMID 39120274, 2024). "Despite the crucial role played by apoptosis-related genes in tumor cell survival, how their expression changes as resistance to EGFR-TKIs emerges remains unclear." (PMID 39122703, 2024). "A study discovered that MET in MET-amplified EGFR-TKI-resistant cells inhibits STING-induced tumor immunogenicity by increasing CD73 expression, serving as a novel immune checkpoint and potential therapeutic target to enhance extracellular adenosine (eADO) production." (PMID 39201787, 2024). "Bufalin’s ability to reduce EGFR expression suggests a complementary mechanism, which could enhance tumor regression when used alongside Cetuximab." (PMID 39123466, 2024).
tumor (continued). "Consequently, patients harboring EGFR mutations or ALK rearrangements demonstrated a diminished PD-L1 and CD8 co-expression level in the tumor microenvironment, potentially contributing to an inadequate response to ICIs." (PMID 38397899, 2024). "In TNBC, CD109 may modulate key inflammatory and tumor-promoting pathways, such as TGF-β, EGFR, and GP130, which are all implicated in TNBC progression." (PMID 39990858, 2024). "We showed that pCASTOR1 scores were significantly higher in tumor cells than non-tumor cells irrespective of the presence of KRAS or EGFR mutations in tumor cells." (PMID 39385301, 2024). "Predictors of positive response to cetuximab therapy include tumor overexpression of EGFR and absence of mutations in the KRAS gene." (PMID 38769503, 2024). "The CheckMate026 study conducted a comparison between nivolumab and platinum-based chemotherapy in patients diagnosed with stage IV NSCLC who had PD-L1 expression levels greater than 5% in their tumor cells and did not have EGFR- or ALK-activating mutations." (PMID 39027681, 2024). "Together, these data indicate that loss of ZNRF3 and RNF43 can promote tumor cell growth through EGFR signaling, sometimes even without substantially engaging canonical WNT signaling." (PMID 38260423, 2024). "The limitations of our study include its retrospective nature, which resulted in missing data that have been previously associated with PFS, such as corrected tumor mutational burden, combinations of STK11, KEAP, and EGFR mutations, human leukocyte antigens, or tertiary lymphoid structure." (PMID 39001553, 2024). "Besides, it has already been demonstrated that several distinct molecular features contribute to the heterogeneity of NSCLC apart from EGFR tumor clonality that arises during cancer development and treatment." (PMID 39497713, 2024). "GEM enhanced the protein levels of c-CBL E3 ubiquitin ligase and triggered the ubiquitination and degradation of the epidermal growth factor receptor (EGFR), thereby reducing the downstream functions of EGFR, including tumor cell proliferation, angiogenesis and metastasis." (PMID 38343880, 2024). "Excitingly, a recent study found that treatment with anti-mouse VEGF antibodies improved both the distribution and infiltration of CAR T cells targeting EGFR VIII in GBM, which resulted in both prolonged survival and slowed tumor growth compared to EGFR VIII CAR T cell therapy by itself." (PMID 39364321, 2024). "Tumor-targeting molecules, including folate, porphyrins, arginine–glycine–aspartic acid (RGD) peptide, and monoclonal antibody targeting epidermal growth factor receptor (EGFR), have been used to make potential tumor-targeting probes for tumor diagnosis and imaging." (PMID 38930839, 2024). "Finally, Western blot analysis revealed that rAREG exposure led to activation of additional tumor cell growth pathways downstream of EGFR, illustrated by increased p-ERK and p-AKT levels starting at 15 min of exposure in both OVCAR8 and PEA1 cells." (PMID 38831884, 2024). "Therefore, targeting EGFR and/or integrin αVβ3 with specific inhibitors or antibodies/small molecules can disrupt these signaling pathways, inhibiting tumor growth and spread." (PMID 39126121, 2024). "Finally, inhibition of HPRT1 coupled with EGFR-TKIs significantly inhibits the tumor growth of EGFR-mutant LUAD." (PMID 39343971, 2024). "Importantly, As2O3 and arsenic sulfide remarkably inhibit the NSCLC stem cells, responsible for chemotherapy resistance (e.g., cisplatin and gefitinib) and tumor recurrence via targeting EGFR pathways, ABC family transporters, and GS-X pumps." (PMID 39717738, 2024). "As 90% of HNSCC overexpress the gene for the epidermal growth factor receptor (EGFR), a targeted antibody therapy to EGFR, cetuximab, has been examined in combination with radiation therapy and has been observed to decrease locoregional tumor burden and reduce mortality." (PMID 38355949, 2024).
tumor (continued). "Additionally, it is used as monotherapy for first-line treatment of adult patients with metastatic NSCLC whose tumors have a PD-L1 expression in ≥ 50% tumor cells or ≥ 10% tumor-infiltrating immune cells and lacks EGFR or ALK genomic tumor aberrations." (PMID 38384472, 2024). "Furthermore, we observed high levels of factors associated with tumor cell proliferation (CDCP1, EpCAM, EGFR, and PDGFB)." (PMID 38942797, 2024). "Indeed, it is known that even small numbers of active EGFR molecules are sufficient to drive tumor cell (and presumably Ba/F3 cell) proliferation." (PMID 38182677, 2024). "PROGENy enrichment analysis further validated the molecular pathway differences between subgroups, which showed that C2 and C3 were significantly enhanced in pathways related to tumor development and metastasis, including EGFR, Hypoxia, MAPK, PI3K, VEGF, and WNT pathways." (PMID 39247607, 2024). "Aberrant activation of EGFR signaling pathways is one of the mechanisms of tumor development." (PMID 38230218, 2024). "The case series reported in this article aim to illustrate the clinical relevance of RAS mutations identified in ctDNA samples of patients with mCRC with a baseline RAS wild-type tumor tissue and who received an anti-EGFR monoclonal antibody plus chemotherapy as first-line treatment." (PMID 39064004, 2024). "They show anti-tumor activity against various targets such as EGFR, vascular endothelial growth factor (VEGF), PD-1, CTLA-4, receptor activator of nuclear factor-kappa B ligand (RANKL), insulin-like growth factor 1 receptor (IGF-1R), human epidermal growth factor receptor (HER2), cMET, and AXL." (PMID 38927911, 2024). "EGFR-TKIs inhibit tumor growth by blocking the ATP-binding site in the EGFR kinase domain." (PMID 38764025, 2024). "In addition, the GEM implant local delivery of gemcitabine inhibits tumor cell growth by promoting c-CBL-mediated EGFR degradation, thus inhibiting the proliferation, angiogenesis, and epithelial mesenchymal metastasis of pancreatic tumor." (PMID 39130630, 2024). "The literature supports that overexpressed wild-type EGFR and EGFR variant III (EGFRvIII) are not independent predictors of median OS in patients who did not undergo extensive tumor resection." (PMID 38882229, 2024). "This study investigated the association between OS and various factors, including gender, age, distinct tumor grades, the extent of resection, multiple surgeries, radio- and chemotherapy received, mutational profiles in IDH1 and TERTp, EGFR amplification, and MGMTp-met." (PMID 38893240, 2024). "For the H358 xenografts, ability to perform analysis was limited by the facts that tumors in this model were highly necrotic, and the tumor volumes were much smaller compared with the tumors that grew for 3 weeks of treatment, providing sufficient material only to analyze EGFR." (PMID 38639476, 2024). "Future experiments are needed to prove whether inhibiting the secretion of PD-L1-positive sEVs by EGFR-mutant NSCLC tumor cells could synergistically enhance the efficiency of PD-L1/PD-1 inhibitors." (PMID 39062533, 2024). "Comprehensive molecular profiling of NSCLC has defined genetic alterations that drive tumor growth, including somatic mutations in KRAS (32.2 %), EGFR (11.3 %), and NF1 (8.3 %) as well as chromosomal fusion events involving receptor tyrosine kinases (RTKs) such as ALK, ROS1, and NTRK1." (PMID 38702301, 2024). "Therefore, exploring the relationship between tumor-specific or other relevant blood markers and prognosis following EGFR-TKI therapy is rational." (PMID 39071492, 2024).
tumor (continued). "Notably, ERK signaling is associated with the upregulation of epidermal growth factor receptor (EGFR) ligands, such as TGF-α, establishing an autocrine feedback loop that sustains tumor progression." (PMID 39682234, 2024). "However, there were notable differences in tumor-size kinetics between antiangiogenic agents and anti-EGFR mAbs; the addition of anti-EGFR mAbs produced a larger treatment effect on the DpR12." (PMID 39587053, 2024). "By targeting CBL-c, it may be possible to disrupt EGFR recycling and enhance lysosomal degradation, thereby inhibiting EGFR activation and potentially limiting tumor growth in NSCLC." (PMID 39130630, 2024). "However, it has been shown that sortilin can limit EGFR signalling by promoting its internalisation, demonstrating a potential tumour-suppression function in the context of cancers dependent on receptor kinase signalling pathways." (PMID 38893272, 2024). "Epidermal growth factor receptor over-expression was observed in 22% of the tumor samples." (PMID 39405290, 2024). "The expression levels of EGF-EGFR-RAS signaling marker genes EGF, EGFR, HRAS, RASSF1 and STK4 in the HLX22 and HLX02 combination-treated cells decreased, suggesting that HLX22 in combination with HLX02 inhibited EGF-EGFR-RAS signaling to suppress tumor proliferation, survival, and invasion." (PMID 38982548, 2024). "In the EGFR signaling pathway, AM produced local proliferation and was gradually polarized into tumor-promoting the M2 phenotype, which mediates drug resistance by inhibiting tumor cell apoptosis and other mechanisms." (PMID 38787372, 2024). "One possibility could be the inhibition of the EGFR pathway to reduce the tissue regeneration potential in the tumor, for example, with a combination therapy of CAR T cells and Cetuximab." (PMID 38226976, 2024). "Additionally, we didn’t have all the molecular tumor characteristics such as NRAS and BRAF mutations, which also affect the response to anti-EGFR antibody therapy." (PMID 39202071, 2024). "Particularly, in GB, miR-7 was shown to act as a tumor suppressor miRNA, as it directly targets the epidermal growth factor receptor (EGFR) gene and negatively regulates the AKT signaling pathway through the direct inhibition of its upstream regulator, the insulin receptor substrate 2 (IRS2)." (PMID 38473710, 2024). "They identified and elucidated the death of tumour cells overexpressing EGFR." (PMID 38999115, 2024). "Additionally, amivantamab enhances immune-mediated tumor cell destruction by inducing Fc-mediated phagocytosis and natural killer cell cytotoxicity against cells expressing EGFR and c-MET." (PMID 38892105, 2024). "Additionally, based on tumor progression from hyperplasia to invasive carcinoma, a gradual increase in EGFR expression has been observed." (PMID 39035991, 2024). "Tumor tissues were collected from patients with NSCLC during their initial surgery, and molecular profiling was performed to identify individuals harboring EGFR-activating mutations (L858R and ex19del)." (PMID 38689087, 2024). "EGFR genotyping is generally based on sequence analysis of tumor DNA isolated from biopsy samples." (PMID 38953007, 2024). "Anti-angiogenesis and anti-EGFR inhibitors possess disparate mechanisms of anti-tumor action." (PMID 38242940, 2024). "It has been suggested that resistance to ICI in EGFR-mutated NSCLC is due to reduced TMB in the EGFR-mutant group compared with wildtype EGFR, or a ‘cold’ uninflamed tumor microenvironment which is immunosuppressive and reduced interferon gamma signature due to CD73 overexpression." (PMID 38339280, 2024). "However, the tumor volume was significantly decreased by OXP in combination with the EGFR inhibitor gefitinib." (PMID 38370387, 2024). "Secondly, our study did not detect other causes of tumor heterogeneity, such as EGFR-mutant or ALK-translocated." (PMID 39729352, 2024).